C6orf15 (chromosome 6 open reading frame 15)
Synonyms: STG
Tractability: Antibody: UniProt places it where antibodies can reach, with medium confidence; UniProt predicts a signal peptide or a membrane-spanning region; its Gene Ontology location is reachable by antibodies, with medium confidence.
Safety:
Unwanted effects reported when the protein is acted on. In parentheses: how it was acted on, where the effect was seen, and who reports it.
thrombocytopenia (source: ClinPGx)
Gene: Protein-coding gene on chromosome 6 (31,111,223 to 31,112,575, reverse strand). Ensembl gene ENSG00000204542.
Subcellular location: Secreted, extracellular space, extracellular matrix
Gene Ontology:
Molecular function: protein binding
Genetic constraint (gnomAD): Loss-of-function variants: 6 observed, 3.69 expected, observed/expected ratio (o/e) 1.62, 90% interval 0.79 to 1.94. That is too few expected variants to judge how well the gene tolerates losing a copy. Missense variants: 363 observed, 430.12 expected, observed/expected ratio (o/e) 0.84, 90% interval 0.77 to 0.92. Synonymous variants: 145 observed, 167.24 expected, observed/expected ratio (o/e) 0.87, 90% interval 0.76 to 1.
Homologues: Orthologues: chimpanzee C6H6orf15 (98% identical), macaque C4H6orf15 (88% identical), pig C6orf15 (65% identical), dog C6orf15 (58% identical), rabbit C6orf15 (57% identical), rat AABR07044373.1 (49% identical), mouse 2300002M23Rik (47% identical).
Diseases named in the same sentence as C6orf15 in open-access papers:
C6orf15 is named in the same sentence as 17 diseases in open-access papers, as found by Europe PMC text mining. Sharing a sentence is not in itself a finding about the gene and the disease. The quoted sentences say what the papers report.
colon cancer (2 papers, 2024). "Previous relevant studies C6orf15 promotes the occurrence and development of colon cancer by promoting the ECM receptor interaction pathway, Hedgehog signalling pathway and WNT signaling pathway." (PMID 38654238, 2024). "We found a close correlation between increased C6orf15 expression and the occurrence of colon cancer." (PMID 38654238, 2024). "To investigate the function of C6orf15 in vivo, we constructed a mouse colon cancer cell line, MC38, that stably overexpressed C6orf15 and assessed the effect of C6orf15 on the liver metastasis of CRC via a liver metastasis (splenic injection) model." (PMID 38654238, 2024). "In colon cancer, C6orf15 is highly expressed in tumor tissues, correlating with adverse pathological features and a poor prognosis." (PMID 38840833, 2024). "In our study, C6orf15 activated the WNT signalling pathway and promoted the nuclear translocation of β-catenin to induce the EMT in colon cancer, and coincidentally, we found an increase in the FAO rate and an increase in the expression of CPT1A after C6orf15 overexpression." (PMID 38654238, 2024).
follicular lymphoma (2 papers, 2024). Follicular lymphoma is a form of non-Hodgkin lymphoma characterized by a proliferation of B cells whose nodular structure of follicular architecture is preserved. "GWAS analysis identified a strong association of C6orf15 with occurrence of follicular lymphoma." (PMID 39484215, 2024). "The function of C6orf15 has not been clearly elucidated, and previous studies have noted that it is expressed in the skin and tonsils, which may be associated with susceptibility to follicular lymphoma." (PMID 38654238, 2024).
systemic lupus erythematosus (2 papers, 2023 to 2024). An autoimmune multi-organ disease typically associated with vasculopathy and autoantibody production. "C6orf15 was reported to be associated with liver cancer prognosis, lymphoma susceptibility, and systemic lupus erythematosus." (PMID 37180113, 2023). "C6orf15 is a novel gene that has been reported only in Sjogren’s syndrome and systemic lupus erythematosus patients." (PMID 38654238, 2024).
colorectal cancer (1 paper, 2024). A primary or metastatic malignant neoplasm that affects the colon or rectum. "The aim of this study was to explore the potential of C6orf15 as a therapeutic target for colorectal cancer." (PMID 38654238, 2024). "Western blot and PCR were used to assess C6orf15 expression in colorectal cancer tissue samples." (PMID 38654238, 2024).
hypotrichosis (1 paper, 2020). A congenital condition, usually due to genetic aberrations, that is characterized by a lack of hair growth on the head and/or body. "Although the deletion encompasses several other genes (C6orf15, PSORS1C1, PSORS1C2, CCHCR1 and part of TCF19), these patients show a phenotype resembling that of PSD without hypotrichosis." (PMID 31663161, 2020).
psoriasis (1 paper, 2021). An autoimmune condition characterized by red, well-delineated plaques with silvery scales that are usually on the extensor surfaces and scalp. "Two of these signals tagged classical HLA alleles identified by HLA sequencing, while the third signal located near a major risk locus for psoriasis that encompassed CDSN, PSORS1C1/PSORS1C2 and C6orf15." (PMID 34879060, 2021).
rheumatoid arthritis (1 paper, 2014). A chronic, systemic autoimmune disorder characterized by inflammation in the synovial membranes and articular surfaces. "mir1286 down regulates C6orf15 and MMEL1; and alteration at these processes favor rheumatoid arthritis, and development and fertilization of ova." (PMID 24587348, 2014).
tumor (5 papers, 2019 to 2024). "C6orf15 expression in stage IV tumours was notably greater than that in the preceding three stages, implying a potential association between elevated C6orf15 expression and CRC metastasis." (PMID 38654238, 2024). "For malignant tumours, C6orf15 may be a novel biomarker for hepatocellular carcinoma, but the role of this gene in other types of tumours deserves further exploration." (PMID 38654238, 2024). "The highest average expression values, calculated across all cancer samples, have candidate tumor-specific antigens ACTL8 (ranked 2nd), MAGEA6 (ranked 14th) and C6orf15 (ranked 8th) with a normalized count expression of 2167.8, 981.4 and 787.0 respectively." (PMID 31069014, 2019).
cancer (4 papers, 2019 to 2023). A tumor composed of atypical neoplastic, often pleomorphic cells that invade other tissues. "Moreover, DSG1, C6orf15, SOST, SPRR2A, SERPINB7, MYBPH, and KRT1 were considerably expressed in the high-risk group, indicating their potential roles as cancer-promoting genes in the development of BLCA." (PMID 37664033, 2023). "Furthermore, the expression of QPCTL was positively correlated with SAA1, POSTN, PLA2G2A, SAA2,C6orf15, H19, PI3, etc., whose expression also affects cancer progress." (PMID 37063864, 2023).
C6orf15 also shares sentences with these, for which no sentence is quoted: breast carcinoma (1 paper); COVID-19 (1); liver cancer (1); lymphoma (1); non-melanoma skin carcinoma (1); Obesity (1); Sjogren syndrome (1); thyroid cancer (1).